HMGA1 (high mobility group AT-hook 1)
Diseases named in the same sentence as HMGA1 in open-access papers (continued):
Sharing a sentence is not in itself a finding about the gene and the disease.
tumor (continued). "This work contributes to the understanding of how differential HMGA1 expression is involved in chromatin organization during cellular differentiation processes and it may help to comprehend effects of HMGA1 over-expression occurring in malign or benign tumours." (PMID 20701767, 2010). "Our findings highlight a novel paradigm where HMGA1 and FGFBP1 drive tumor progression and angiogenesis, presenting them as potential therapeutic targets for HNSCC." (PMID 41943828, 2026). "High mobility group proteins (HMGA1, HMGA2, HMGB1) and miR-106a-5p are involved in tumor progression, but their interplay in UC remains incompletely understood." (PMID 41828319, 2026). "To unravel the downstream oncogenic signaling triggered by secreted HMGA1, we conducted phosphoproteomic analysis, identifying hyperphosphorylation of Nucleophosmin 1 (NPM1), as a pivotal event that further amplifies tumor cell proliferation." (PMID 41145488, 2025). "A recent paper demonstrated that EWS-FLI1 and CD99 simultaneously inhibit miR-214-3p function, leading to a failure to inhibit High-mobility group protein A1 (HMGA1) protein, thereby maintaining the undifferentiated state and tumor aggressiveness." (PMID 40427525, 2025). "To determine more precisely how HMGA1 modulates tumorigenesis in CDX2P-CreERT2Apcfl/fl mice, we compared colon weights as a surrogate for tumor burden since extensive, contiguous tumors in the proximal colon precludes precise enumeration." (PMID 39895630, 2025). "HMGA1 recruits FANCD2 to protect stalled replication forks from degradation and assists with unwinding the R-loop, ultimately increasing the ability of tumor cells to cope with replication stress." (PMID 40288645, 2025). "The expression levels of G6PD, HMGA1, MKI67, RACGAP1, and RFC4, were significantly higher in tumor samples with (p < 0.05)." (PMID 40421085, 2025). "In NSCLC, HMGA1 interacts with STMN1 to regulate its phosphorylation levels at Ser16 and Ser38, thereby reducing microtubule stability and promoting tumour metastasis." (PMID 39828988, 2025). "Once in the extracellular space, HMGA1 initiates autocrine or paracrine signaling leading to the hyperphosphorylation of NPM1, thereby promoting tumor proliferation." (PMID 41145488, 2025). "To further assess the effect of HMGA1 depletion on PARP1 inhibition, we tested the effect of olaparib on tumours generated from HMGA1‐manipulated AKR cells in a syngeneic mouse model." (PMID 39690136, 2024). "Our findings revealed that the TFs E2F1, HMGA1, MYC, FOSL1 and CREB3 exhibited exceptional levels of activity within C2 UBE2C+ tumour cells." (PMID 38894657, 2024). "To observe the effect of xenografts on tumor growth in vivo, we used a nude mouse model to evaluate the effect of 786-O PTBP3 KD cells and HMGA1 overexpression in 786-O PTBP3 KD cells on tumor growth." (PMID 38405614, 2024). "To determine the role of HMGA1 in the maintenance of malignant phenotype of ESCC, we investigated the impact of HMGA1 manipulations on ESCC cell proliferation and tumor growth." (PMID 39080260, 2024). "Significant change of expression, reaching 10- to 58-fold change between uterine lesion compared to non-tumor counterpart, was observed in CAPN6, CD24, HMGA1, PLAG1, SNORA48, and SNORD10 (upregulation) and DKK3 and STK26 (downregulation)." (PMID 37466765, 2024). "Therapeutics targeting TKT with an inhibitor, oxythiamine, reduced HMGA1-induced ESCC cell proliferation and tumor growth." (PMID 39080260, 2024). "The authors showed that binding of miR-142-3p to the 3′ non-coding region (3′UTR) in HMGA1, HMGA2, HMGB1, and HMGB3 mRNAs leads to apoptosis of tumor cells, as well as to decreased proliferation, migration, and invasion." (PMID 39062899, 2024).
tumor (continued). "Strikingly, there was a marked decrease in tumor volumes in mice treated with BLU9931, along with decreased staining for HMGA1, FGF19, Ki-67, and fibrosis (trichrome)." (PMID 36919699, 2023). "In xenograft tumours, GATM knockdown suppressed the expression of MYC, HMGA1, and HMGA2, and GAA diet feeding stimulated their expression." (PMID 37370109, 2023). "Our results reveal what we believe is a new paradigm whereby HMGA1 and FGF19 drive tumor progression and stroma formation, thus illuminating FGF19 as a rational therapeutic target for a molecularly defined PDAC subtype." (PMID 36919699, 2023). "Among the target genes of miR-635, HMGA1, a small nuclear protein belonging to the HMGA family, is an oncofoetal gene and regulates genesis and development of various neoplasms." (PMID 35692504, 2022). "Control (shCTRL) and HMGA1-depleted (shHMGA1) MDA-MB-231 cells were injected subcutaneously into the fat pads of nude mice and, when tumours reached palpable masses (50–100 mm3), mice were treated with paclitaxel three times a week for 5 weeks." (PMID 35504904, 2022). "PIT1, as a key transcription factor in pituitary development, after E2F1 binds to the HMGA1 promoter to increase the expression of HMGA1, and PIT1 tends to show a higher level in tumours." (PMID 35864955, 2022). "It has been shown that HMGA1 can induce stem-cells features in TNBC and its silencing impairs tumour growth, reverses EMT and in vivo tumorigenesis in MDA-MB-231 orthotopic xenografts." (PMID 35267409, 2022). "Among BC patients both HMGA1 and stathmin are expressed at high levels in the basal-like and the HER2+ subtypes, ER-negative, and high-grade tumours." (PMID 35504904, 2022). "The results indicated that low levels of HMGA1 and LINC00152 arrest cell cycle progression and inhibit GC cell proliferation, suggesting that LINC00152 promotes tumor growth and can form a ceRNA network with HMGA1 to regulate the proliferation of GC cells." (PMID 35014092, 2022). "Altogether highlights a crucial role of HMGA1 in the progression of TNBC and its great value as prognosis predictor in these tumours." (PMID 35267409, 2022). "We found that paclitaxel treatment reduced the tumour volume in mice injected with shCTRL MDA-MB-231 cells and with shHMGA1 MDA-MB-231 cells, but this effect is much stronger in HMGA1-depleted cells compared to the control." (PMID 35504904, 2022). "AC also suppressed the expression of Ki-67, HMGA1, N-cadherin, and hnRNPA1 and enhanced the expression of E-cadherin, GRP78, and Chop in tumor tissues." (PMID 35692504, 2022). "HMGA1 expression can be regulated by KIFC1, which is involved in the aerobic glycolysis of UCEC cells leading to proliferation of tumor cells." (PMID 36253800, 2022). "In TNBC, Extracellular HMGA1 can be used as the ligand of receptor for advanced glycation end products (RAGE) to form an HMGA1-RAGE autocrine loop and induce pERK signalling to increase the migration and invasion ability of tumour cells." (PMID 35864955, 2022). "The tumor stem cell score based on the one-class logistic regression (OCLR) algorithm showed that HCG18 and its regulated transcription factors HMGA1, ILF2, and YBX1 positively correlated with the degree of tumor undifferentiation." (PMID 34527669, 2021). "Here, HMGA1 downregulation was also found to inhibit cell viability, migration, and invasion in GBC, suggesting that HMGA1 is a tumor promoter in GBC." (PMID 34090483, 2021). "The results showed that relative to normal samples, proteins (LAMC2, HMGA1, CSTB) were significantly upregulated in tumor tissues." (PMID 34732701, 2021). "HMGA1 and ILF2 were highly expressed in tumor stem cell-like cells, while YBX1 was highly expressed in both monocyte macrophages and tumor stem cell-like cells." (PMID 34527669, 2021). "HCG18 participates in vascular invasion of HCC by regulating macrophages and tumor stem cells through three key transcription factors, YBX1, ILF2, and HMGA1." (PMID 34527669, 2021).
tumor (continued). "In osteosarcoma, the circRNA hsa_circ_0005909/miR-338-3p/HMGA1 axis promotes tumor cells proliferation; the CASC15/miR-338-3p/RAB14 axis induces tumor cells growth, migration, and invasion in vitro and in vivo." (PMID 34718336, 2021). "It has been reported that both HMGA1 and HMGA2 are high expressed in HGSOC and correlated with tumor progression and poor prognosis." (PMID 32127525, 2020). "More recently, HMGA1 was shown to interact with the FOXM1 transcription factor for VEGFA promoter binding, inducing tumor angiogenesis in HUVEC cells and in zebrafish xenografts." (PMID 31963852, 2020). "HMGA1 induces STAT3 expression that has a main role in inflammation, malignant transformation, and tumor progression; STAT3 overexpression also leads to hematologic malignancies." (PMID 32503270, 2020). "HMGA1 and HMGA2 are involved in the EMT process, both during development (e.g., in NCCs) and in tumor progression." (PMID 31963852, 2020). "Other evidence of the role of HMGA1 and HMGA2 in maintaining a stem cell state has been found in different types of tumor cells, among which we will only provide a few examples." (PMID 31963852, 2020). "Our data clearly show that HMGA1 and FOXM1, in addition to regulating VEGFA, have a strong impact on tumor angiogenesis." (PMID 31311575, 2019). "The detection of changes in the subcellular localization and or the levels of HMGA1 in CTCs could offer the potential to more accurately predict patient outcomes than classical tumor response assessment methods, such as radiological evaluation or serum tumor markers." (PMID 31779212, 2019). "Our data demonstrate a synergic role of HMGA1 and FOXM1 in governing tumor angiogenesis using an in vivo model." (PMID 31311575, 2019). "A higher expression of HMGA1 mRNA levels in II and III tumor stages was also observed when comparing with IA stage tumor (p = 0.0001)." (PMID 31096664, 2019). "It has also been proposed that HMGA1 can regulate the expression of matrix-metalloprotease 2 (MMP2), and hence tumor invasion." (PMID 31779212, 2019). "Overall, these results suggest that in MDA-MB-231 cells, the presence of HMGA1 is relevant for both RSK2 and CBP activities and that together, these two factors cooperate in the expression of genes critical for tumor cell migration and aggressiveness." (PMID 31382504, 2019). "HMGA1, RSK2, and CBP control the expression of a set of genes involved in tumor progression and epithelial to mesenchymal transition." (PMID 31382504, 2019). "Specifically, HMGA1 enhances E2F transcriptional activity by directly binding RB1, inhibiting its tumor suppressive activity." (PMID 31311575, 2019). "The expression of both HMGA1 and HMGA2 has been shown to correlate with advanced tumour stages and metastasis in PDAC patients." (PMID 30228296, 2018). "In tumours from KP172CT;Hmga2CK/+ mice, Hmga1 and Hmga2 were expressed in primary tumour areas as well as in metastases in liver and lung." (PMID 30228296, 2018). "We found a dramatic upregulation of the canonical NOTCH1 target gene HEYL and a concurrent downregulation of HMGA1 and HMGA2 in fibroblasts co-cultured with JAG1-expressing tumour cells, particularly A549 and Hep3B cells." (PMID 29743479, 2018). "In conclusion, our studies strongly support the finding that, at least in DDLS and MLS, the HMGA1/E2F1 and NFkB pathways are involved in the mechanism of tumor progression and trabectedin resistance." (PMID 29980789, 2018). "Neoplastic phenotypes appeared in Hmga1−/− and Hmga1+/− mice, suggesting a possible role of HMGA proteins in tumor suppression." (PMID 27538817, 2016). "The integration from our omics-based research provides a four molecular pathway foundation (ANXA2/HMGA1/POU3F1; NFRSF13/GSN; TMOD3/RAI14/VWF; and PLAT/PLAU) behind HO-1 regulation of tumor cytoskeletal cell compartments." (PMID 28032857, 2016). "The tumor expressed HMGA2 and HMGA1 even though 12q14-15 and 6p looked normal by G-banding analysis." (PMID 25621995, 2015).
tumor (continued). "The HMGA1/HPRT expression levels ranged from 0.21 to 2.02 within the control samples and from 0.36 to 1.28 within the tumour samples." (PMID 25245141, 2014). "HMGA1/HPRT expression ranged from 1 to 1.31 in the non neoplastic and 0.269 to 0.811 within the tumour samples." (PMID 25245141, 2014). "HMGA1/GUSB expression levels varied from 0.225 to 1.47 within the control samples, and from 0.53 to 2.52 within the tumour samples." (PMID 25245141, 2014). "Screenings as done herein exemplarily for the HMGA2 regulator let-7a and the HMGA2 targets HMGA1, SNAI1, SNAI2 and CDH1 will help to reveal the tumour acting mechanisms." (PMID 24914948, 2014). "There is twice as much Hmga2 expression in both primary tumour cells and (Lin−) LacZ+ FACS-sorted tumour cells, than the Hmga1 expression profile in the same cells." (PMID 23307470, 2013). "Interestingly, in HMGA1-depleted cells, the disorganised morphology changed to acini-like spheroids with hollow lumens typical of non-malignant breast epithelial cells, confirming that HMGA1 may be involved in the tumour cell differentiation process." (PMID 23945276, 2013). "In accord with their tumor-suppressive role, members of the let-7 family target cell cycle regulators and oncogenes like RAS, HMGA1/2, MYC, IGF2BP1 and LIN28." (PMID 21835047, 2011). "HMGA1 and HMGA2, two other key factors in tumor progression that are controlled by the let-7 family, support the RAS/MEK-facilitated induction of EMT by enhancing SNAIL expression." (PMID 21835047, 2011). "Interestingly, both HMGA1 and 2 overexpression may relate to tumour metastasis in WNECs." (PMID 19156147, 2009). "This suggests that in KRAS-mutant PDAC, tumor progression and stromal formation may be further promoted by FGF19 through its synergistic action with HMGA1." (PMID 41328353, 2026). "Blocking HMGA1, FGFBP1, or FGFR1 also reduced stromal formation and increased tumor necrosis." (PMID 41943828, 2026). "We identified six signature LRGs (ALB, G6PD, HMGA1, MKI67, RACGAP1, and RFC4) possess prognostic potential, correlation with immune infiltration, and lactylation-related pathways, providing novel insights into tumor microenvironment (TME) of HCC." (PMID 40421085, 2025). "High-mobility protein A1 (HMGA1) can affect the transcription of tumor-related genes through different pathways, and its increased expression can accelerate tumor infiltration and metastasis, which is not conducive to disease prognosis." (PMID 40636372, 2025). "HMGA1 and HMGA2 are two important members of it and play an important role in tumor progression." (PMID 38405614, 2024). "Since HMGA1 and PARP1 synergistically promote DNA damage repair, we hypothesized that inhibiting HMGA1 could sensitize tumour cells to PARP1 inhibitors like olaparib." (PMID 39690136, 2024). "While HMGA1 knockdown or olaparib alone failed to control tumour proliferation, their combination effectively inhibited tumour growth." (PMID 39690136, 2024). "Moreover, treatment with an FGF receptor 4 (FGFR4) inhibitor, BLU9931, to block FGF19 function recapitulates the effects of HMGA1 or FGF19 silencing, decreasing tumor growth and stroma formation in orthotopic models." (PMID 36919699, 2023). "Moreover, decreased HMGA1 expression in a xenograft mouse model, resulting from knockdown of an upstream long non-coding RNA regulator, correlated with delayed GBM tumor growth and increased survival." (PMID 38259614, 2023). "While we could not dissect the contribution of the stroma in isolation, our models suggest that HMGA1 and FGF19 collaborate to promote tumor progression and stroma formation." (PMID 36919699, 2023). "HMGA1 was highly expressed in A549/DDP and H1975/DDP cells or DDP-resistant tumor tissues." (PMID 36304135, 2022).
tumor (continued). "HMGA1 can positively influence both histone H3S10 phosphorylation by ribosomal protein S6 kinase alpha-3 (RSK2) and histone H2BK5 acetylation by CREB-binding protein (CBP) regulating the expression of a set of genes involved in tumor progression and EMT." (PMID 36614035, 2022). "The high mobility group AT-hook 1 (HMGA1) is a non-histone chromatin-binding protein that is overexpressed in several tumor types and is associated with tumor invasion, metastasis, and drug resistance." (PMID 35563845, 2022). "This study is advantaged at the identification and validation of a novel 2-TF signature consisted of HMGA1 and MAFG, which is able to predict the prognosis and therapeutic response of HCC via distinguishing the characteristics of tumor proliferation and metabolism." (PMID 36685838, 2022). "High HMGA1 protein expression in NSCLC tissue was connected with a higher TNM stage and HMGA1 gene overexpression with shorter overall survival and increased HMGA1 protein levels in tumor tissue among NSCLC patients." (PMID 35805937, 2022). "Immunohistochemistry (IHC) staining indicated that HMGA1 protein expression was higher in tumor tissues than in nontumor tissues from the HPA." (PMID 35014092, 2022). "In addition, the expression of p27 mRNA in BC patients inversely correlates with that of HMGA1, being lower in the basal-like and HER2+ subtypes, with respect to the other subtypes, in the ER-negative subgroup and in high-grade tumours." (PMID 35504904, 2022). "Furthermore, AC administration suppressed the expressions of Ki-67, HMGA1, N-cadherin, and hnRNPA1 and increased the expressions of E-cadherin, GRP78, and Chop in tumor tissues (P < 0.01)." (PMID 35692504, 2022). "Although HMGA1 is known to be an oncogene, its tumor-promoting function is still not fully studied because its tissue-specificity and that it is involved in convergence of many signal pathways." (PMID 33648560, 2021). "HMGA1 was positive in six out of six non-tumor MF samples and negative in five out of five tumor MF samples." (PMID 34831413, 2021). "A recent study also found that HMGA1 downregulates NUMB in brain tumor stem cells, which could maintain the tumor cells in a more de-differentiated, stem-like state and contribute to tumor progression." (PMID 34572547, 2021). "HMGA1 was positive in six of six non-tumor MF samples and negative in five of five tumor MF samples." (PMID 34831413, 2021). "Functionally, HMGA1 promotes CCA cell proliferation/invasion and xenograft tumor growth." (PMID 34716319, 2021). "In addition, LAMC2, HMGA1 and CSTB were discovered to be upregulated significantly along with trajectory transition and elevated in the metastatic tumor lesions, which was consistent with published researches focusing on biological roles of LAMC2/ HMGA1." (PMID 34732701, 2021). "Furthermore, lncRNA TTN-AS1 acted as a tumor promoter in GBC by sponging miR-107 and upregulating HMGA1." (PMID 34090483, 2021). "LncRNA TTN-AS1 acted as a tumor promoter in GBC by sponging miR-107 and upregulating HMGA1." (PMID 34090483, 2021). "Interestingly, the tumor tissues with low expression of SLC25A26 had high expression of proliferation index Ki67, while the senescence markers p16, p21, HMGA1 had low expression, and the tissue of high expression of SLC25A26 showed the opposite results." (PMID 33041323, 2020). "One of the genes uncovered in the neural crest cluster was Hmga1, a non-histone chromatin remodeler that has known roles in tumor metastasis, but has been understudied in development." (PMID 32965216, 2020). "In contrast, the neighboring protein-coding gene HMGA1 was found to be significantly overexpressed in both tumor datasets relative to matched non-malignant tissue." (PMID 33505435, 2020). "In general, high levels of DDX39A and PBX1 were found in all tumor samples while HMGA proteins showed poor (HMGA1) or no (HMGA2) endogenous expression in tumor cells." (PMID 31188873, 2019).